TOP3A (DNA topoisomerase III alpha)
Description:
Releases the supercoiling and torsional tension of DNA introduced during the DNA replication and transcription by transiently cleaving and rejoining one strand of the DNA duplex. Introduces a single-strand break via transesterification at a target site in duplex DNA. The scissile phosphodiester is attacked by the catalytic tyrosine of the enzyme, resulting in the formation of a DNA-(5'-phosphotyrosyl)- enzyme intermediate and the expulsion of a 3'-OH DNA strand. The free DNA strand then undergoes passage around the unbroken strand thus removing DNA supercoils. Finally, in the religation step, the DNA 3'-OH attacks the covalent intermediate to expel the active-site tyrosine and restore the DNA phosphodiester backbone. As an essential component of the RMI complex it is involved in chromosome separation and the processing of homologous recombination intermediates to limit DNA crossover formation in cells. Has DNA decatenation activity. It is required for mtDNA decatenation and segregation after completion of replication, in a process that does not require BLM, RMI1 and RMI2.
Synonyms: TOP3; ZGRF7; MGRISCE2; PEOB5
Tractability: PROTAC: ubiquitination databases record sites on it.
Gene: Protein-coding gene on chromosome 17 (18,271,428 to 18,315,007, reverse strand). Ensembl gene ENSG00000177302.
Subcellular location: Mitochondrion matrix
Pathways (Reactome):
DNA Repair: HDR through Homologous Recombination (HRR); HDR through Single Strand Annealing (SSA); Homologous DNA Pairing and Strand Exchange; Presynaptic phase of homologous DNA pairing and strand exchange; Processing of DNA double-strand break ends; Resolution of D-loop Structures through Holliday Junction Intermediates; Resolution of D-loop Structures through Synthesis-Dependent Strand Annealing (SDSA)
Disease: Defective HDR through Homologous Recombination Repair (HRR) due to PALB2 loss of BRCA1 binding function; Defective HDR through Homologous Recombination Repair (HRR) due to PALB2 loss of BRCA2/RAD51/RAD51C binding function; Defective homologous recombination repair (HRR) due to BRCA1 loss of function; Impaired BRCA2 binding to PALB2; Impaired BRCA2 binding to RAD51
Cell Cycle: G2/M DNA damage checkpoint
DNA Replication: Strand-asynchronous mitochondrial DNA replication
Reproduction: Meiotic recombination
Gene Ontology:
Molecular function: DNA topoisomerase type I (single strand cut, ATP-independent) activity; protein binding; single-stranded DNA binding; DNA binding; DNA topoisomerase activity; zinc ion binding
Biological process: chromosome separation; DNA topological change; double-strand break repair via homologous recombination; mitochondrial DNA metabolic process; resolution of DNA recombination intermediates; meiotic cell cycle
Cellular component: mitochondrial matrix; mitochondrion; PML body; RecQ family helicase-topoisomerase III complex; nucleoplasm; nucleus; chromosome
Genetic constraint (gnomAD): Loss-of-function variants: 56 observed, 94.92 expected, observed/expected ratio (o/e) 0.59, 90% interval 0.47 to 0.74. The upper end of that interval is the gene's LOEUF score, 0.74, which puts it in group 3 of 6, group 1 being the genes least tolerant of losing a copy. Missense variants: 998 observed, 1,211.6 expected, observed/expected ratio (o/e) 0.82, 90% interval 0.78 to 0.87. Synonymous variants: 451 observed, 462.72 expected, observed/expected ratio (o/e) 0.97, 90% interval 0.9 to 1.05.
Homologues: Orthologues: chimpanzee TOP3A (99% identical), macaque TOP3A (97% identical), dog TOP3A (88% identical), rat Top3a (87% identical), mouse Top3a (87% identical), guinea pig TOP3A (86% identical), pig TOP3A (84% identical), rabbit TOP3A (83% identical), tropical clawed frog top3a (69% identical), zebrafish top3a (65% identical), Drosophila melanogaster Top3alpha (49% identical), Caenorhabditis elegans top-3 (36% identical). Paralogues in human: TOP3B (29% identical).
Diseases named in the same sentence as TOP3A in open-access papers:
TOP3A is named in the same sentence as 37 diseases in open-access papers, as found by Europe PMC text mining. Sharing a sentence is not in itself a finding about the gene and the disease. The quoted sentences say what the papers report.
Bloom syndrome (9 papers, 2009 to 2025). Bloom syndrome (BSyn) is a rare chromosomal breakage syndrome characterized by a marked genetic instability associated with pre- and postnatal growth retardation, facial sun-sensitive telangiectatic erythema, increased susceptibility to infections, and predisposition to cancer. "A recent report has modelled the effect of a Bloom syndrome-causing TOP3A truncating mutation in mice." (PMID 41189053, 2025). "Mutations on BLM and the TRR (TOP3A/RMI1/RMI2) subcomplex have been linked to Bloom syndrome (BS) or BS-like genetic disorders, predisposing individuals to cancer development." (PMID 40846865, 2025). "High‐molecular‐weight mtDNA remained visible following expression of several pathological TOP3A variants, particularly Leu37Val, Arg558Trp and the two Bloom syndrome‐associated variants Ala176Val and Ser810LeufsTer2 (expressed as Ser810*)." (PMID 37013609, 2023). "Both of these Bloom syndrome‐associated variants also showed only a limited capacity to ameliorate the mtDNA copy number loss and structural phenotypes associated with TOP3A depletion in rescue experiments." (PMID 37013609, 2023). "The prior probabilities were considered relatively high (0.1) due to the impact of mutations in BLM for cancer risk in Bloom syndrome patients and the functional relevance of the TOP3A for the BLM complex." (PMID 19432957, 2009). "The truncating p.Ser810LeufsTer2 variant, also identified in patients with Bloom syndrome, removes almost 200 amino acids of the poorly characterised C‐terminus of TOP3A, including predicted zinc finger motifs of unknown function." (PMID 37013609, 2023). "Loss‐of‐function variants in BLM, a binding partner of nuclear TOP3A, cause Bloom syndrome, a rare recessive disorder characterised by short stature, predisposition to cancer and a photosensitive (butterfly) rash, associated with an elevated rate of sister chromatid exchanges." (PMID 37013609, 2023). "Using recombinant TOP3A variants with in vitro model substrates together with cellular rescue experiments, we characterise the molecular defects associated with mutated TOP3A, including variants found in patients with primary mitochondrial disease and a Bloom syndrome‐like disorder." (PMID 37013609, 2023). "BLM, the helicase mutated in Bloom syndrome, is found in protein complexes together with topoisomerase IIIa (TOP3A) and a newly identified member, the RECQ-mediated genome instabilitity 1 (RMI1) protein, that process double Holliday junction intermediates into non-crossover recombinants." (PMID 19432957, 2009). "Equivalent reactions using pathological variant‐containing forms of TOP3A found that the p.Leu37Val and p.Met575Val variants found in the mitochondrial patient cohort, as well as the p.Ala176Val variant found in Bloom syndrome, showed a marked loss of decatenation activity." (PMID 37013609, 2023). "This phenotype could again be rescued by expression of WT TOP3A (lane 5) but only partially rescued by the expression of several pathological variants, including Arg103Gln, Arg558Trp, Met575Val and the Bloom syndrome‐associated variants Ala176Val and Ser810* (lanes 6–13)." (PMID 37013609, 2023). "The higher frequency of origin firing observed in TOP3A mutant and deficient cells is likely a compensatory mechanism triggered by the slower fork progression to guarantee the full duplication of the genome without increasing the length of the S-phase, as previously observed in Bloom syndrome cells." (PMID 37024461, 2023). "Pathogenic variants in TOP3A can cause a disorder similar to Bloom syndrome, which results from bi‐allelic pathogenic variants in BLM, encoding a nuclear‐binding partner of TOP3A." (PMID 37013609, 2023). "This disorder shares a number of features with Bloom syndrome, which is caused by biallelic loss-of-function mutations in BLM, one of the binding partners of TOP3A in the nucleus." (PMID 34547213, 2021).
Bloom syndrome (continued). "Several of these patients also presented with cardiomyopathy, not typically associated with Bloom syndrome, and likely related to the additional mitochondrial role of TOP3A." (PMID 37013609, 2023). "We previously reported a single patient with a complex adult‐onset mitochondrial disorder characterised by PEO and prominent cerebellar features, but without evidence of Bloom syndrome, resulting from bi‐allelic TOP3A gene variants; additional families have since been described." (PMID 37013609, 2023). "However, a number of these patients with truncating variants in TOP3A also exhibited cardiomyopathy, not typically observed in Bloom syndrome, that is likely to be attributable to the loss of activity of the mitochondrial isoform of TOP3A." (PMID 34547213, 2021). "Therefore, it is suggested that individuals in the Bloom syndrome registry lacking molecular diagnosis may have causative variants in other genes as RMI1, RMI2, or TOP3A genes with the overlapping phenotypic manifestation." (PMID 37052241, 2023).
osteosarcoma (6 papers, 2012 to 2025). A usually aggressive malignant bone-forming mesenchymal neoplasm, predominantly affecting adolescents and young adults. "We and others have previously reported amplification of TOP3A, encoding a type 1 topoisomerase, in osteosarcomas." (PMID 22292074, 2012). "The results emphasize the potential interest in developing TOP3A inhibitors for treatment of ALT‐positive ATRX‐wt osteosarcomas." (PMID 35920001, 2022). "One of the main discoveries of our study is that TOP3A amplification and ATRX mutation are mutually exclusive genomic events in ALT‐positive high‐grade osteosarcoma." (PMID 35920001, 2022). "This seems to contradict the hypothesis that in osteosarcoma, either ATRX mutations or TOP3A overexpression are needed for ALT." (PMID 40725011, 2025). "However, prognostic studies for the other candidate genes require the development of new antibodies (C17orf39, RICH2, RASD1) or testing of available antibodies on osteosarcoma tissues (TOP3A, COPS3, SHMT1, PRPSAP2, PMP22), which is presently underway." (PMID 22292074, 2012). "Although TOP2A and TOP3A are different types of isomerases, one may speculate that amplification and overexpression of TOP3A has an oncogenic effect similar to that of TOP2A on the development of osteosarcoma and other cancers." (PMID 22292074, 2012). "Previous studies have reported that various pathogenic variants of TOP3A lead to the instability of mitochondrial and nuclear genomes in different clinic disorders, including Bloom syndrome-like disorder, pediatric osteosarcomas and adult-onset mitochondrial disease." (PMID 41168351, 2025). "It was found that in ATRX wild-type pediatric osteosarcomas with alternative lengthening of telomeres (ALT), TOP3A is required for proper BLM localization, and TOP3A amplification promotes ALT DNA synthesis." (PMID 38534397, 2024). "Of note, overexpression of genes belonging to the amplified region (COPS3, PMP22, GID4, ARGHAP44, TOP3A, SHMT1, and RASD1) was studied in osteosarcoma cell lines." (PMID 35920001, 2022). "Amplification of 17p11.2 chromosomal region containing TOP3A led to increased expression of TOP3A, which supported the maintenance of telomeres through the alternative lengthening of telomeres (ALT) mechanism in osteosarcoma." (PMID 37197432, 2023). "Here, we report that most high‐grade pediatric osteosarcomas maintain their telomeres by ALT, and that the majority of these ALT tumors are ATRX wild‐type (wt) and instead carry an amplified 17p11.2 chromosomal region containing TOP3A." (PMID 35920001, 2022). "Here, we have shown that TOP3A amplification and overexpression is an alternative to ATRX inactivation, and the most frequent genetic event identified in ALT‐positive high‐grade pediatric osteosarcoma." (PMID 35920001, 2022). "Based on our statistical analysis of the correlation between copy number increase and expression level for each of the top ranking genes, we identified RICH2, c17orf45, TOP3A, COPS3, SHMT1, PRPSAP2, PMP22, and RASD1 as candidate osteosarcoma oncogenes in the 17p11.2-p12 region." (PMID 22292074, 2012). "However, in contrast to TOP3A and NBS1, MMS21 amplification was also observed at high frequency in ALT‐negative tumors, suggesting that it does not have a specific role in the maintenance of ALT telomeres in pediatric osteosarcomas." (PMID 35920001, 2022). "Among the 10 ALT osteosarcoma cell lines, 5 harbored ATRX alterations and no TOP3A amplification, 2 harbored no ATRX alteration and TOP3A amplification, and 3 neither of the 2; statistical analysis, however, gave a non-significant result (p = 0.44)." (PMID 40725011, 2025).
bladder cancer (3 papers, 2009 to 2024). "Interestingly, in the late-stage bladder cancer cohort, we observed that high expression of TOP3A associated with stage IV disease." (PMID 37669321, 2023). "This suggests that TOP3A is associated with the development of metastatic disease, but its expression may result in the development of a bladder cancer phenotype that is more sensitive to checkpoint immunotherapy." (PMID 37669321, 2023). "In this study we have studied 26 tagged single nucleotide polymorphisms (tagSNPs) in RMI1, TOP3A, and BLM and their associations with cancer risk in acute myeloid leukemia/myelodysplatic syndromes (AML/MDS; N = 152), malignant melanoma (N = 170), and bladder cancer (N = 61)." (PMID 19432957, 2009). "In TOP3A, rs12945597 was associated with increased risk for AML/MDS and malignant melanoma, and showed a non-significantly increased risk for bladder cancer." (PMID 19432957, 2009).
breast carcinoma (3 papers, 2009 to 2024). "The rs12945597 in TOP3A and rs2532105 in BLM was significantly associated with increased breast cancer risk." (PMID 19432957, 2009). "For further analysis of breast cancer, rs12945597 in TOP3A, rs401549, and rs2532105 in BLM were selected, as well as rs1563634 in TOP3A, which showed similar non-significant protective effects in all three cancer forms for the variant homozygous carriers." (PMID 19432957, 2009). "An allele-dosage effect was found for the combination rs12945597 (TOP3A) and rs2532105 (BLM) for AML/MDS, bladder and breast cancer, where carriers with two variant alleles displayed the highest risks." (PMID 19432957, 2009). "The rs12945597 in TOP3A and rs2532105 in BLM showed increased risk for breast cancer." (PMID 19432957, 2009). "In order to test this hypothesis we analysed in this study polymorphisms in the RMI1, TOP3A and BLM, and their association with cancer risk in available case-control materials, namely AML/MDSs (acute myeloid leukemia and myelodysplastic syndromes), malignant melanoma, and bladder and breast cancer." (PMID 19432957, 2009).
myelodysplastic syndrome (3 papers, 2009 to 2024). A clonal hematopoietic disorder characterized by dysplasia and ineffective hematopoiesis in one or more of the hematopoietic cell lines. "TOP3A is underexpressed in ovarian cancer, and mutations in TOP3A are associated with increased risk for acute myeloid leukemia and myelodysplastic syndromes, suggesting potential cancer vulnerabilities if somatic, but they can also occur in the germline, which would lead to enhanced host toxicity." (PMID 31575041, 2019).
External ophthalmoplegia (2 papers, 2019 to 2024). Paralysis of the external ocular muscles. "Biallelic mutation of TOP3A is reported in a patient suffering from chronic progressive external ophthalmoplegia (CPEO), characterized by muscle-restricted mtDNA deletions." (PMID 31597307, 2019). "Chronic progressive external ophthalmoplegia (CPEO) plus syndrome due to pathogenic biallelic missense variants in the TOP3A gene may be associated with reduced TOP3A activity, affecting its mitochondrial functions." (PMID 38534397, 2024).
lung adenocarcinoma (2 papers, 2017 to 2021). A carcinoma that arises from the lung and is characterized by the presence of malignant glandular epithelial cells. "Increased mRNA expression of TOP3A is correlated with worse prognosis in non-small-cell lung cancer and lung adenocarcinomas." (PMID 34009545, 2021). "Especially, high expression of two topoisomerase isoforms, TOP2A and TOP3A, was found to be correlated to worse overall survival (OS) in all NSCLC and lung adenocarcinoma (Ade) patients, but not in lung squamous cell carcinoma (SCC) patients." (PMID 28355294, 2017).
malignant melanoma (2 papers, 2009 to 2021). "In melanoma brain metastases, heterozygous copy number loss of HR and SSB repair, but no mismatch repair-associated genes, was found, which from the most prevalent genes were APTX, FEN1, GTF2H5, DNA2, MUS81 and TOP3A." (PMID 34885093, 2021).
cardiomyopathy (1 paper, 2021). A disease of the heart muscle or myocardium proper. "A further two siblings were also recently reported with a Bloom syndrome-like disorder with cardiomyopathy and mitochondrial dysfunction, resulting from compound heterozygous truncating and missense variants in TOP3A." (PMID 34547213, 2021).
leishmaniasis (1 paper, 2023). Infectious disease that is transmitted through the bite of hematophagous female phlebotomine sand flies. "Bioinformatics and expression studies led to the identification of the candidate gene Top3a that might influence resistance to leishmaniasis and, for the first time, highlighted the potential role of this gene in infection biology." (PMID 37600780, 2023). "Thus, Top3a might be indirectly or directly involved in the immune response against leishmaniasis." (PMID 37600780, 2023).
lymphoma (1 paper, 2025). A malignant (clonal) proliferation of B- lymphocytes or T- lymphocytes which involves the lymph nodes, bone marrow and/or extranodal sites.
metastatic disease (1 paper, 2023). "Interestingly, we observed increased expression of TOP3A in stage IV tumors, suggesting a role in metastatic disease, yet we also observed that the same gene was more expressed in tumors that responded to immunotherapy." (PMID 37669321, 2023).
microcephaly (1 paper, 2021). A congenital or acquired developmental disorder in which the circumference of the head is smaller than normal for the person's age and sex. "Several other DNA damage response proteins, which are binding partners of BRCA1 (such as SLX4, TOP3A, RNF168, and MCPH1) are also associated with microcephaly." (PMID 33441416, 2021). "Among them, two groups of excitatory neurons, THEMIS-PLA2G7 and FEZF2-SCN7A, express several PSGs involved in DNA damage response and mutated in patients with microcephaly such as BRCA1, NHEJ1, RNF168, and TOP3A." (PMID 33441416, 2021). "Among those, a number of DNA damage response genes associated with microcephaly in humans such as BRCA1, NHEJ1, TOP3A, and RNF168 show strong signs of positive selection and might have played a role in human brain size expansion during primate evolution." (PMID 33441416, 2021).
sarcoma (1 paper, 2025). A usually aggressive malignant neoplasm of the soft tissue or bone. "In sarcomas, TOP3A amplification is a known driver of ALT in ATRX wild-type tumors, and this alteration has also been observed in pediatric HGG." (PMID 41422096, 2025).